IL6 (interleukin 6)
Diseases named in the same sentence as IL6 in open-access papers (continued):
Sharing a sentence is not in itself a finding about the gene and the disease.
Obesity (continued). "Several previous studies have also reported a similar negative correlation between serum IL-6 and testosterone, with the majority of these investigators suggesting that the observed increase in IL-6/inflammation with obesity was due to a withdrawal of testosterone’s immunosuppressive effect." (PMID 28286655, 2017). "However, we were unable to detect statistically significant differences in inflammatory cytokines that are traditionally associated with obesity including TNF-α and IL-6, two standard markers of an inflammatory response." (PMID 28873415, 2017). "It was previously shown that mice lacking gene encoding IL-6 develop mature onset obesity, suggesting an important role of IL-6 in the regulation of body weight." (PMID 29163240, 2017). "Furthermore, this IL-6 inflammatory response, mediated by chondrocyte-synovial fibroblast cross-talk, was enhanced by the obesity-related adipokine leptin." (PMID 28615667, 2017). "As in obesity, this may contribute to an increase in inflammatory mediators (TNFα and IL-6), a decrease in adiponectin, and potentially insulin resistance." (PMID 28212318, 2017). "Adipose tissue secretes a variety of biologically active factors, including the anti-inflammatory adipokine adiponectin, which is reduced in obesity, and proinflammatory cytokines such as tumor necrosis factor (TNF)α and interleukin (IL)-6, which are increased in obesity." (PMID 28929125, 2017). "Metabolic by-products characteristic of obesity augment the permeability of the blood-brain barrier and induce a sustained liberation of pro-inflammatory cytokines (e.g., interleukin-6, or IL-6), which ultimately increase the activity of the hypothalamic-pituitary-adrenal (HPA-) axis." (PMID 29375342, 2017). "While most adipokines are upregulated in obesity and promote inflammatory responses (e.g., Leptin, TNFα, IL-6, and IL-18), others may act as anti-inflammatory modulators (e.g., adiponectin, and secreted frizzled related protein 5)." (PMID 28758929, 2017). "Indeed, in obesity, the circulating levels of IL-6 correlate with adiposity and IL-6 expression increases in the adipose of obese patients." (PMID 28632778, 2017). "In addition, choline deficiency is associated with increased levels of several inflammatory markers that link obesity to obesity-associated diseases, including CRP, homocysteine, IL-6, and TNF." (PMID 28403191, 2017). "In 2002 Wallenius found that IL-6 was increased in obesity and responsible for insulin resistance." (PMID 28344817, 2017). "Although numerous mechanisms such as change in gut peptides and reduced neurotrophic factors are suggested, increased pro-inflammatory cytokines like IL-6 might also be important contributor in hippocampal injury in obesity." (PMID 29281967, 2017). "This study suggests that obesity enhances the cross-talk between chondrocytes and synovial fibroblasts via raised levels of the pro-inflammatory adipokine leptin, leading to greater production of IL-6 in OA patients." (PMID 28615667, 2017). "Obesity may cause chronic, low-grade systemic inflammation through increased levels of TNF-α, IL-6, leptin, free fatty acids, and TLR4 and decreased adiponectin levels." (PMID 29049401, 2017). "Obesity is now regarded as an inflammatory condition, which is characterized by increased production and secretion of pro-inflammatory cytokines such as TNFα and IL-6." (PMID 29025435, 2017). "Moreover, levels of IL‐6 in cerebrospinal fluid (CSF) were reported to be inversely correlated with obesity in humans." (PMID 29024103, 2017). "Obesity is associated with chronic low-grade inflammation of white adipose tissue (WAT), in which there is upregulated secretion of the pro-inflammatory cytokines TNF-α, IL-1β and IL-6." (PMID 27840174, 2017). "The primary source of circulating IL-6 in obesity could be macrophages that have infiltrated white adipose tissue and accumulated during obesity due to local hypoxia." (PMID 28061787, 2017).
Obesity (continued). "Antipsychotics can increase rates of obesity, with consequent upregulation of IL-6, and leptin." (PMID 29163240, 2017). "These elevations in cardiovascular risk factors during pregnancy are further worsened in clinical states such as gestational diabetes, pre-eclampsia or obesity, which are associated with a poorer lipid profile, insulin resistance and elevated high-sensitivity CRP, IL-6 and TNF-α." (PMID 28193219, 2017). "Interleukin-6 (IL-6) is a crucial regulator of T cells and is increased in obesity." (PMID 28466852, 2017). "The recent data show that IL-6 exhibits anti-inflammatory properties during obesity by promoting IL-4-dependant alternative macrophage polarization thus contributing to attenuation of obesity-induced inflammation and regulation of glucose homeostasis." (PMID 29163240, 2017). "Moreover, skeletal muscle-specific JNK-1 deficiency revealed a minor role in glucose metabolism, whereas WAT-specific JNK-1 deletion decreased obesity-induced IL-6 levels and thus ameliorated diet-induced insulin resistance." (PMID 28233125, 2017). "Besides leptin, other pro-inflammatory cytokines - Interleukin-6 (IL-6) and tumor necrosis factor (TNF) are linked strongly to obesity and have been found to have a role in development of CC." (PMID 28819564, 2017). "Moreover, both MeS and obesity are characterized by the activation of several inflammatory pathways, including cytokines as Interleukin-6, Tumor Necrosis Factor-alpha, Interleukin-1 and adipokines as leptin, adiponectin and resistin." (PMID 29112985, 2017). "A potential aspect that may explain these differences might be the chronic/constant presence of IL-6 under obesity conditions." (PMID 28233125, 2017). "We extended this exploration to pre-adipocytes, CD31+ endothelial cells and mature adipocytes, focusing on a set of inflammation-related genes (CCL2, CCL20, IL-8, IL-6 and pro-IL-1β) selected among genes known to be up-regulated in adipose tissue with human obesity." (PMID 28592801, 2017). "In the paradigm of inflammation within obesity, it is hypothesized that IL-6 enhances the prevailing inflammation, thus precipitating insulin resistance and leading to further micro- and macrovascular complications." (PMID 29163354, 2017). "Supporting the role of obesity in MS pathophysiology, five week calorie restriction has been shown to significantly reduce inflammation and demyelination, correlated with increased serum adiponectin and reduced IL-6 and leptin in EAE mice." (PMID 28708082, 2017). "In fact, IL-6 and IL-1β are positive modulators of insulin resistance in adipose tissue and the heart during obesity, which might be of medical interest." (PMID 29201273, 2017). "Consistently, clinical studies link obesity-induced insulin resistance with increased IL-6 levels." (PMID 28233125, 2017). "In addition, elevated expression was seen for IL-6 in adipose tissue in connection to obesity and insulin resistance." (PMID 28763032, 2017). "Interleukin-6 (IL-6) is increased in obesity and activates T cells to promote inflammation." (PMID 28466852, 2017). "Taken together, the role of elevated IL-6 levels in depressed patients may need to be interpreted in a sex-specific manner as well as to include other confounding factors such as obesity." (PMID 29176959, 2017). "With the aim to gain a better insight into the relationship between obesity and breast cancer risk, we sought to clarify the contribution of individual adipokines (adiponectin, leptin, and IL-6 etc.) to obesity, and to provide a reference for breast cancer biomarkers." (PMID 29088874, 2017). "In obesity, macrophages infiltrate adipose tissue and begin to induce proinflammatory cytokines, such as interleukin-1 beta (IL-1β), tumor necrosis factor alpha (TNFα), and interleukin-6 (IL-6), which can interfere with insulin signaling in adipocytes." (PMID 27066503, 2016).
Obesity (continued). "Diet-induced obesity did not alter expression of Tnfa, Nos2, Il12, Il10, but was associated with a significant increase in Retnla expression and a small reduction in Il6, and Arg1 expression." (PMID 26956558, 2016). "Interestingly, IL-6 levels are elevated in obesity and positively correlate with BMI, and a role for IL-6 in tumorigenesis has been demonstrated in animal models." (PMID 27494857, 2016). "Consistently, IL-6 knockout mouse exhibit obesity and glucose intolerance." (PMID 28025491, 2016). "Mature adipocytes are not only a lipid storage site but also produce and secrete different adipokines and factors such as leptin, interleukin (IL)-6, and vascular endothelial growth factor (VEGF), which are closely associated with angiogenesis and other pathological conditions in obesity." (PMID 27527145, 2016). "In contrast, increased methylation of IL6 was associated with risk of obesity and body weight among patients without diabetes." (PMID 26911440, 2016). "Thus, Arg-II-expressing macrophages facilitate diet-induced NAFLD through TNF-α and IL-6 in obesity." (PMID 26846206, 2016). "Compared to individuals with normal weight individuals with obesity have higher levels of circulating tumor necrosis factor-α (TNF-α) and interleukin-6 (IL-6), which are also secreted from adipose tissue and are involved in the pathophysiology of both obesity and periodontitis." (PMID 27590050, 2016). "Obesity is associated with adipose tissue inflammation and increased secretion of proinflammatory adipokines such as adipocyte fatty acid-binding protein (A-FABP), tumor necrosis factor-alpha (TNF-α), and interleukin-6 (IL-6)." (PMID 27819006, 2016). "Obesity and T2DM, which are associated with insulin resistance, have been shown to have fat cell dysfunction that results in the production of an excessive amount of proinflammatory adipokines such as IL-6 and TNF-α." (PMID 27379252, 2016). "Obesity is a state characterized by a massive infiltration of adipose tissue by macrophages, the activity of which contributes to insulin resistance by the excessive release of pro-inflammatory cytokines such as TNFα or IL-6." (PMID 27983705, 2016). "However, obesity was associated with VAT, since IL-6 and IL-15 were significantly more in obese individuals compared to normal-weight ones, whereas, the cytokines difference was not significant between two groups in SAT related cytokines expression." (PMID 27703587, 2016). "Obesity causes a low-grade inflammation and is associated with a chronic inflammatory response and increased levels of tumor necrosis factor-α (TNF-α), interleukin-6 (IL-6) and/or C-reactive protein (CRP)." (PMID 27136447, 2016). "Interaction effects between dietary FAs and variations in inflammation-related genes such as tumor necrosis factor α (TNF-α) and interleukin 6 (IL6) may influence obesity phenotypes." (PMID 26999109, 2016). "In conclusion, our data support a model in which human obesity leads to the elevated expression of IL-6R and IL-6 in the adipose tissue, with increased tissue expression of TNF-α, MCP-1, IP-10 and infiltration by CD11b+/CD163+ macrophages as the underlying features of meta-inflammation." (PMID 26200663, 2015). "Therefore, we determined the obesity-related changes in the adipose tissue expression of IL-6 receptor (IL-6R) and IL-6 and assessed their relationship with signature inflammatory mediators or markers in this compartment." (PMID 26200663, 2015). "ADIPOQ and IL6 variants were not directely related to obesity, leptin resistance or alterations in cardiometabolic markers." (PMID 25897330, 2015). "In accordance with our hypothesis, these results provide further evidence for the presence of a low-grade systemic inflammation in obesity, in which more than the commonly described adipokines IL-1, IL-6 and TNF-α are involved." (PMID 25781614, 2015).
Obesity (continued). "Our findings may reflect a difference in regulation of ZIP14 following an LPS induced- acute inflammatory state with a strong IL-6 response vs. the chronic inflammation found in obesity." (PMID 26623077, 2015). "In hypertrophic adipose tissue (a frequent characteristic of obesity), NF-κB and HIF-1α are capable of overregulating the expression of genes that encode proinflammatory cytokines, such as IL-6 and TNF-α which, in turn, have direct deleterious effects on the insulin cell signaling pathway." (PMID 25944984, 2015). "It is the M1 macrophage phenotype which is associated with obesity and adipose tissue inflammation, is responsible for TNF-α and IL-6 production, and may predominate during the early stages of tumorigenesis." (PMID 26132316, 2015). "It was, therefore, concluded that obesity was a positive modulator of IL-6R and IL-6 expression in the adipose tissue which might be a contributory mechanism to induce metabolic inflammation." (PMID 26200663, 2015). "Adiposity, especially abdominal obesity, is the strongest predictor of hsCRP concentrations across different populations, probably resulting from obesity-induced up-regulation of the cytokines IL-6 and TNF-α which contributes to low-grade inflammatory and hsCRP elevation." (PMID 26365713, 2015). "This notion is mainly based on the hypothesis that obesity per se increases inflammation, i.e., proinflammatory cytokines like IL-1β and IL-6 due to an increased leakiness of the gut barrier in obese individuals." (PMID 26421054, 2015). "We also identified a potential interaction between obesity and IL-6 among normal-weight and overweight participants: IL-6 appeared to be positively associated with QUICKI and capillary density (beneficial effect), but the inverse was true among obese individuals." (PMID 26549941, 2015). "Although IL-6 production is associated with visceral fat, the relationship between IL-6 and obesity is not straightforward." (PMID 26217222, 2015). "Between these cytokines, IL-6 displays pleiotropic role in metabolism and obesity." (PMID 26635627, 2015). "In case-control studies, plasma IL-6 levels are increased in GDM independently of obesity, and may be a significant predictor of GDM." (PMID 26110385, 2015). "The link between obesity inflammation, and abnormal glucose metabolism may in part be related to increased production of pro-inflammatory cytokines such as IL-6 and TNF-α in adipose tissue." (PMID 25994228, 2015). "IL-6 produced in skeletal muscle is released in the circulation after prolonged physical activity which may exert anti-obesity effect on liver and adipose tissue via glucose homeostasis and exercise-induced lipolysis." (PMID 26200663, 2015). "Interestingly, T-box transcription factor (T-bet) absence, a key factor to development of Th1 cell, leads to obesity possibly by IL-6 up-regulation." (PMID 26635627, 2015). "With elevated levels of IL-6 associated with type II diabetes and obesity we anticipated a decrease in IL-6 with CR, however this was not evident here." (PMID 26061745, 2015). "IL-6 and TNF-α have been observed to have a positive association with obesity in urban dwellers." (PMID 26391589, 2015). "Another example of the relation of disorders of obesity and inflammation is interleukin 6 (IL-6)." (PMID 26869866, 2015). "Inflammation, obesity, stress and coronary heart disease: is interleukin-6 the link?" (PMID 26301005, 2015). "Obesity is considered a state of chronic inflammation as an increase in adipose tissue mass results in greater secretion of inflammatory markers including C-reactive protein, interleukin-6, interleukin-1β, and tumor necrosis factor-α." (PMID 26150767, 2015). "However, local levels of TNF-α, IL-6 and IL-1 in the placenta are greater in women with obesity compared to healthy controls." (PMID 26569331, 2015).
Obesity (continued). "Inflammation is part of the physiopathology of obesity and high levels of pro-inflammatory cytokines such as IL6, IL-8 and Serpin E1 could link together inflammation and adipose tissue remodeling." (PMID 25816202, 2015). "We also found that the mitochondria-related miR-141-3p might promote the pro-inflammatory cytokine (IL-6) expression, inducing the inflammatory response and contributing to the development of obesity." (PMID 26548909, 2015). "In human obesity, it has been suggested that a major source of IL-6 is adipose tissue." (PMID 26121241, 2015). "Above findings suggested that the mitochondria-related miR-141-3p might promote the pro-inflammatory cytokine (IL-6) expression, inducing the inflammatory response and contributing to the development of obesity." (PMID 26548909, 2015). "We next asked whether the enhanced adipose tissue expression of IL-6R and IL-6 in obesity was related to the tissue inflammatory state represented by ATM colonization." (PMID 26200663, 2015). "Adipose tissue is an important source of circulating IL-6 and the expanding adipose tissue in obesity may contribute high levels of IL-6 in the circulation." (PMID 26200663, 2015). "It is estimated that about 35% of obesity-related IL-6 in serum is secreted from adipose tissue." (PMID 25926797, 2015). "It is also unclear how the adipose tissue expression of IL-6R and IL-6 is modulated by obesity." (PMID 26200663, 2015). "Indeed, obesity is described as being a state of low-grade chronic inflammation in which increased IL-6, IL-8, and TNF-α levels have been described as obesity-induced risk factor of CVD." (PMID 25918477, 2015). "A link between obesity and inflammation has been initially hypothesized based on the observation of increased levels of IL-6 and C-reactive protein (CRP) in obese animals and humans." (PMID 26089771, 2015). "Interestingly, linear regression analysis revealed that serum levels of IL-6 and haptoglobin play a significant role in the pathogenesis of obesity." (PMID 27275205, 2015). "Adipose tissue mass accumulation in the visceral region during obesity has been associated with elevated levels of inflammatory mediators, including serum C-reactive protein (CRP), acute phase proteins and pro-inflammatory cytokines TNF-α and IL-6." (PMID 24979131, 2014). "Accumulating evidence suggests that obesity—in particular central/visceral accumulation of fat—and its co-morbidities correlate with increases in circulating levels of inflammatory proteins such as C-reactive protein and IL-6." (PMID 24447654, 2014). "Furthermore, obesity induces chronic inflammation in adipose tissue, increasing pro-inflammatory cytokines including interleukin-6 and tumour-necrosis factor." (PMID 24693947, 2014). "Of note, these chronic inflammatory signals can have a profound impact on CD4+ T cell populations, and it has been shown, in murine studies, that diet-induced obesity can impact specific fat-resident regulatory T cells (Treg) and particularly promote a Th17-biased immunity, partly dependent on IL-6." (PMID 25426122, 2014). "The role IL-6 plays in obesity and IR remains controversial even after many years of research." (PMID 24686488, 2014). "Obesity induces changes in serum levels of insulin sensitizing adipokines and also generates a generalized proinflammatory environment by increasing the circulating levels of resistin, interleukin 6 (IL-6) and tumoral necrosis factor alpha (TNF-α)." (PMID 24949022, 2014). "IL-6 is a multi-functional cytokine that can be produced by adipocytes as well as by different leukocyte types and its production is known to correlate to obesity levels in mammals." (PMID 25333488, 2014). "However, some authors found a correlation between IL-6 and obesity and IR, but the results are still conflicting." (PMID 24736687, 2014). "Obesity-related increase in IL-6 may also contribute to the obesity, and it has been described that increased IL-6 production was linked with high TNFα expression." (PMID 24522555, 2014).